HBA1 (hemoglobin subunit alpha 1)
Description:
Involved in oxygen transport from the lung to the various peripheral tissues. [Hemopressin]: Hemopressin acts as an antagonist peptide of the cannabinoid receptor CNR1. Hemopressin-binding efficiently blocks cannabinoid receptor CNR1 and subsequent signaling.
Synonyms: HBA-T3; ECYT7; HBH; METHBA
Target class: Secreted protein
Safety:
Unwanted effects reported when the protein is acted on. In parentheses: how it was acted on, where the effect was seen, and who reports it.
N/A, Cyanosis occurs (source: AOP-Wiki)
Gene: Protein-coding gene on chromosome 16 (176,680 to 177,522, forward strand). Ensembl gene ENSG00000206172.
Pathways (Reactome):
Cellular responses to stimuli: Cytoprotection by HMOX1; Heme signaling
Transport of small molecules: Erythrocytes take up carbon dioxide and release oxygen; Erythrocytes take up oxygen and release carbon dioxide
Disease: Heme assimilation
Vesicle-mediated transport: Scavenging of heme from plasma
Gene Ontology:
Molecular function: haptoglobin binding; peroxidase activity; protein binding; heme binding; oxygen carrier activity; iron ion binding; oxygen binding
Biological process: hydrogen peroxide catabolic process; inflammatory response; nitric oxide transport; oxygen transport; response to hydrogen peroxide; carbon dioxide transport; erythrocyte development; cellular oxidant detoxification
Cellular component: blood microparticle; extracellular exosome; extracellular region; haptoglobin-hemoglobin complex; hemoglobin complex; membrane; cytosol; endocytic vesicle lumen
Genetic constraint (gnomAD): Loss-of-function variants: 3 observed, 2.89 expected, observed/expected ratio (o/e) 1.04, 90% interval 0.44 to 1.87. That is too few expected variants to judge how well the gene tolerates losing a copy. Missense variants: 41 observed, 57.7 expected, observed/expected ratio (o/e) 0.71, 90% interval 0.55 to 0.92. Synonymous variants: 29 observed, 29.4 expected, observed/expected ratio (o/e) 0.99, 90% interval 0.73 to 1.35.
Gene-disease validity (ClinGen):
ClinGen rates the evidence that HBA1 causes each of these diseases.
erythrocytosis, familial, 7 (autosomal dominant): Moderate.
unstable hemoglobin disease (autosomal dominant): Moderate.
methemoglobinemia, alpha type (autosomal dominant): Limited.
Homologues: Orthologues: macaque HBA (96% identical), macaque HBA1 (96% identical), mouse Hba-a1 (87% identical), mouse Hba-a2 (87% identical), rat Hba-a3 (79% identical), guinea pig GLNC1 (76% identical), dog HBQ1 (73% identical), rat Hba-a2 (67% identical), rat Hba-a3 (65% identical), tropical clawed frog hba1 (58% identical), zebrafish hbae4 (46% identical), Drosophila melanogaster glob1 (21% identical), and 2 more. Paralogues in human: HBA2 (100% identical), HBQ1 (62% identical), HBZ (60% identical), HBM (45% identical), HBB (44% identical), HBD (44% identical), HBG1 (42% identical), HBG2 (42% identical), HBE1 (39% identical), CYGB (32% identical), MB (26% identical).
Diseases named in the same sentence as HBA1 in open-access papers:
HBA1 is named in the same sentence as 125 diseases in open-access papers, as found by Europe PMC text mining. Sharing a sentence is not in itself a finding about the gene and the disease. The quoted sentences say what the papers report.
diabetes (46 papers, 2012 to 2025). "For these reasons, HbA1 C has been endorsed as a diagnostic criterion for diabetes.As an important indicator of long-term blood glucose control, HbA1 C has been closely associated with the risk of developing DR." (PMID 40361041, 2025). "Patients with diabetes are known to carry an increased cardiovascular risk, but that risk decreases as HbA1 C-levels return to normal." (PMID 35268268, 2022). "Several studies found that higher continuity of care was associated with more services used by diabetes patients, including more HbA1 testing and eye or foot examinations." (PMID 35910878, 2022). "Considering the broad informativeness of the HbA1 test, it can be successfully applied to the management and assessment of overall vascular risk in patients with diabetes." (PMID 32403389, 2020). "Thus, for a comprehensive evaluation of diabetes management, GV indexes should always be used in parallel with traditional risk biomarkers such as HbA1 and fasting or post-prandial glycemia." (PMID 38256584, 2024). "In addition, after adjusting gender, ethnicity and duration of diabetes, the interaction of HbA1 with vitamin D deficiency significantly affected retinopathy severity (P=0.029)." (PMID 28604686, 2017). "Another factor that might in part explain the inability of the present study to find a significant association in the non-diabetes group is that HbA1 measurements were obtained in only a small subset of this group, as HbA1c is only reimbursed in Belgium for patients with known diagnosis of diabetes." (PMID 34284809, 2021). "For individuals with diabetes mellitus, HbA1 C serves as a therapeutic target for adjusting glucose-lowering treatments, as it shows a significant correlation with the risk of developing microvascular complications related to diabetes mellitus." (PMID 40361041, 2025). "As a widely used indicator for blood glucose testing, HBA1 reflects average blood sugar levels over the past 2–3 months and serves as a critical marker for assessing diabetes control." (PMID 40299352, 2025). "Other diabetes centers have found an effect on HbA1 c of increased involvement from the diabetes team." (PMID 40303938, 2025). "This assumption is supported by the reported effect of tocotrienol, the rice bran oil fraction, on reducing fasting blood glucose and HbA1 C in a T1D rat model after 8 weeks of diabetes induction." (PMID 40536613, 2025). "Among patients with low adherence to MD, there was a higher prevalence of diabetes mellitus (DM) diagnosis (48.5% vs. 18.9%, p = 0.009) and significantly higher HbA1 levels, and a trend towards lower HDL cholesterol and higher fasting glucose levels." (PMID 39339817, 2024). "This study concentrated on the results of the TyG index, BMI (body mass index), and HbA1 (hemoglobin A1c) to predict the level of diabetic retinopathy in people who have had diabetes for a long time." (PMID 36776951, 2023). "In fact, markers of diabetes, such as fasting blood glucose and HbA1 concentrations, were much less pronounced in Gunn rats with the preservation of insulin secretion by the pancreatic islets of these hyperbilirubinemic animals." (PMID 37445792, 2023). "Diabetes education differs from country to country, and the control of educational strategies by parents and their children regarding HbA1 values that help to prevent long term micro- and macrovascular complications were not controlled in this study." (PMID 26759608, 2016). "Blood samples from our diabetics were analyzed for the oxidative and antioxidant activities, as well as for determining the glycemia, HbA1, HDL/LDL cholesterol, and triglycerides." (PMID 26618168, 2015). "We performed correlations between two numeric variables (such as correlation between microalbuminuria and some parameter like HbA1, creatinine, duration of diabetes, blood urea nitrogen, HDL cholesterol, LDL cholesterol, total cholesterol, and triglycerides)." (PMID 26435566, 2015).
diabetes (continued). "After adjustment for diabetes mellitus, APOA/B, and HbA1, we found thatcompared with the Q1 group, the risk of NTL progression in the other three groupswas increased by 3.06, 3.55 and 7.51, respectively, with statisticallysignificant differences between the groups." (PMID 39139413, 2024). "T2DM patients who have the TT genotype in -262 C/T may have elevated risk of diabetes complications; these patients had the lowest mean CAT and HDL, as well as the highest glucose, HbA1 and TCH levels." (PMID 37759451, 2023). "Interestingly, the changes in the glycocalyx length correlated with the progression of diabetes, as assessed by monitoring the HbA1 concentration, and progressive endothelial dysfunction, as evidenced by the decrease in NO production." (PMID 29162916, 2017). "However, the shrinking of the glycocalyx length in areas with preserved endothelial glycocalyx is a consequence of prolonged diabetes manifested by increased HbA1." (PMID 29162916, 2017). "While there is scarce evidence to link the SFR with HbA1, several studies suggest that patients with diabetes mellitus undergo glandular damage that may translate into a lower salivary flow than in healthy subjects." (PMID 26535097, 2015). "However, the shrinking of the glycocalyx length in areas with preserved endothelial glycocalyx was progressive and correlated with progression of diabetes (assessed based on blood HbA1 concentration) as well as with progressive impairment of endothelial function (NO production)." (PMID 29162916, 2017). "After adjusting age, diabetes duration, FPG and HbA1, we found that the serum level of IAA, CDCA and Cit were still statistically significant in certain groups which were consistent with our results of metabolomics analysis and Elisa." (PMID 36157454, 2022). "Induction of diabetes in male Wistar rats by STZ led to reduction in the body weight with concomitant decrease in the blood insulin levels and increase in the glucose and HbA1 levels." (PMID 23843977, 2013). "Although the relationship between HbA1 and HNSCC has not been thoroughly investigated, it is evident that diabetes and HNSCC share several common risk factors." (PMID 40299352, 2025). "Compared with nondiabetic people, those with diabetes and a HbA1 level <7% and those with a HbA1 level ≥9% both had a higher risk of pneumonia-related hospitalization." (PMID 39195186, 2024). "Furthermore, some women had measurements of blood glucose, determination of HbA1 or HbA1c or laboratory flat charge (EBM Codes 32025, 32057, 32881, 32094) resulting in 90.8% tested for (gestational) diabetes in 2014 rising to 93.3% in 2020." (PMID 37758812, 2023). "Compared with class 1, participants in the other classes had fewer current smokers and drinkers, higher BMI, SBP and DBP, a higher prevalence of hypertension, diabetes, dyslipidemia and heart disease, and had higher FBG, TC, TG, LDL, HbA1 levels and lower HDL levels." (PMID 37296457, 2023). "The negative association of diabetes and AAA pathogenesis was detected by the negative correlation between HbA1 and expansion rate." (PMID 33923412, 2021). "The group with carotid plaque had more male, older, higher prevalence of hypertension, diabetes, higher levels of fasting glucose, HbA1, total cholesterol, LDL-C, and statin than those without plaque." (PMID 33456499, 2020). "We tested with a M-ANOVA the effects of all independent variables only on the duration of diabetes, HbA1 and TGFβ1, because these dependent variables were normally distributed and correlated significantly." (PMID 33334029, 2020). "A meta-analysis that included 13 studies found that high protein diets (protein to energy ratio between 25% and 33%) did not significantly reduce HbA1 c levels (%) in patients with diabetes over a period of 12 weeks to 52 months (−0.05 (95% CI (−0.18 to 0.08, p = 0.92)))." (PMID 36615714, 2022).
diabetes (continued). "What's more, in the group of CKD patients with diabetes, the elevation in levels of CR, BUN, serum phosphorus, ACR, and HbA1 was more pronounced than those without diabetes." (PMID 36046149, 2022).
thalassemia (46 papers, 2016 to 2026). An inherited blood disorder characterized by a decreased synthesis of one of the polypeptide chains that form hemoglobin. "In this cohort, the prevalence of thalassemia, caused by pathogenic variants in HBA1/HBA2 and HBB, was 1/13, which aligns with previously reported findings." (PMID 40421383, 2025). "Our study aimed to investigate if genetic variants around 16p13.3’s HBA1 locus, associated with erythrocyte indices and HbA1c levels, predict α-thalassemia-related erythrocyte indices, cardiometabolic traits, and diabetes risk in Taiwanese individuals." (PMID 37788909, 2023). "First, α-thalassemia is characterized by a deficit in α-globin chain synthesis and most commonly caused by the deletion in the HBA1 gene, which is encoded by α-globin and is localized on chromosome 16p13.3 where the three SNVs are located." (PMID 37788909, 2023). "α-Thalassemia (α-thal) and β-thalassemia (β-thal) are two main types of thalassemia caused by mutations in the HBA1/2 and HBB genes respectively, which result in abnormal α- and β-globin synthesis and defective hemoglobin structure." (PMID 35701592, 2022). "α- and β-Thalassemia are the most common forms of thalassemia, resulting from mutations in the α- and β-globin gene clusters (HBA1, HBA2, and HBB) on chromosome 16 and chromosome 11, respectively." (PMID 35783323, 2022). "The thalassaemia phenotype group describes the allele phenotype and includes HBA1 and HBA2 variants (α+/α0 and α+; total: 146 SNVs) and HBB variants (β0, β0/β+, β+, β++ (silent) and β++; total: 289 SNVs)." (PMID 36453528, 2022). "At present, the detection range of the reagents we used only included 2062 variant sites related to thalassemia on the HBA1/2 and HBB genes." (PMID 34690349, 2022). "Thalassemias are caused by mutations in the α (HBA1/HBA2) and β globin (HBB) genes and are usually inherited in an autosomal recessive manner." (PMID 33072976, 2019). "α-Thalassemia (α-thal) is a genetic disorder caused by the substitution of single amino acid or large deletions in the HBA1 and/or HBA2 genes." (PMID 26824843, 2016). "Notably, both key genes associated with thalassemia, HBA1 and HBA2, are completely deleted, leading to the manifestation of α0-thalassemia." (PMID 40129608, 2025). "This region includes HBM, HBA2, HBA1 and HBQ1, which is associated with the pathogenesis of α-thalassemia." (PMID 41444645, 2025). "Thalassemia is classified into two based on the globin gene defect: alpha-thalassemia (Hemoglobin Subunit Alpha 1: HBA1 and Hemoglobin Subunit Alpha 2: HBA2 genes) and beta-thalassemia (Hemoglobin Subunit Beta: HBB gene)." (PMID 40523316, 2025). "All involved the critical HS-40 regulatory region and both HBA1 and HBA2 structural genes, consistent with α0-thalassemia alleles." (PMID 41009357, 2025). "Although we excluded HBA1, HBA2, and HBB genes causing thalassemia and hemoglobinopathies, the carrier rate of at least one screened disorder was still as high as 14.7% (241/1642) in our cohort." (PMID 38167091, 2024). "The thalassemia genes HBA1 and HBA2 detected in this study are highly homologous, and NGS has certain limitations." (PMID 38660679, 2024). "Globin HBA1/HBA2 testing in this individual confirmed the cis deletion (αα/--) consistent with the α-thalassemia trait." (PMID 39062615, 2024). "A custom-designed liquid phase chip for gene detection associated with thalassemia was then used and confirmed partial deletions of HBA2 (NM_000517) and upstream HBA1 (NM_000558.5) (-α3.7)." (PMID 38982507, 2024). "The SMRT method developed in this study focused on detection of variants in HBA1, HBA2, and HBB genes, which consisted the vast majority of thalassemia variants." (PMID 34690349, 2022). "Using family 13 as an example to analyze α-thalassemia, 138 SNPs within 1 Mb upstream and 132 SNPs within 2 Mb downstream from the HBA1 and HBA2 gene were adopted with sequencing depth > 30X." (PMID 35490243, 2022).
thalassemia (continued). "The a+-thalassemia due to a deletion of 3.7Kb (-α3.7 deletion) is the most common cause of α-thalassemia, which affects both HBA1 and HBA2 genes, resulting in a single hybrid gene (HBA2-HBA1)." (PMID 33769430, 2021). "With the introduction of NGS, retrospective analysis of these samples using the Devyser Thalassemia panel confirmed the MLPA-detected deletions, validating the loss of critical regions including HBA1, HBA2, and HS-40, reinforcing their classification as full α0 deletions." (PMID 41009357, 2025). "In thalassemia diagnostics, the Comprehensive Analysis of Thalassemia Alleles (CATSA) framework achieved 100% accuracy for rare variants like the α3.7III subtype by spanning GC-rich HBA1/HBA2 loci." (PMID 41301752, 2025). "Long-range PCR and long-molecule sequencing on the PacBio Sequel II platform utilized in this study could cover the entire HBA1, HBA2 and HBB genes, enabling the diagnosis of most of the common and rare types of thalassemia variants." (PMID 35701592, 2022). "Compared to conventional methods, SMRT technology detected more abnormal hemoglobin variant sites on the HBA1, HBA2, and HBB genes, which illustrated the value of SMRT technology in the diagnosis of common and rare types of α-thalassemia and β-thalassemia variants." (PMID 34690349, 2022). "Moreover, there are other α-thalassaemia deletions of varying sizes around the world that can involve one or both of theHBA genes (HBA1 andHBA2)." (PMID 34632085, 2020). "For example, the hemoglobin α1 gene (HBA1) in α-thalassemia patients is repressed by antisense transcription, where an aberrant LUC7L (putative RNA-binding protein Luc7-like) RNA runs antisense to the HBA1 locus and methylates the CpG island at the promoter to repress the HBA1 gene expression." (PMID 30669611, 2019). "For traditional thalassemia genetic diagnosis, the reverse dot blot hybridization, Sanger sequencing, GAP-PCR and Multiple ligation-dependent probe amplification (MLPA) can be utilized to detect the prevalent variants, including SNVs, indels and copy number variations in HBB and HBA1/212." (PMID 35701592, 2022). "The α-globin genes (HBA1, HBA2, and the unique HBA12) were frequently involved in α-thalassemia, with the -α3.7 deletion predominating." (PMID 41929524, 2026). "We observed that 23.8% of individuals were carriers of thalassemia and hemoglobinopathies (HBB, HBA1, and HBA2), followed by 7.7% who were carries of G6PD deficiency." (PMID 38167091, 2024). "More than 250 single nucleotide variants (substitutions, microdeletions, or microduplications) relate to α-thalassemia and are more often observed in HBA2 gene than HBA1." (PMID 38542374, 2024). "By way of contrast, in the case of α-thalassemia, Hb electrophoresis test results are normal, and MLPA of HBA1/HBA2 can diagnose the most common deletions." (PMID 36832257, 2023). "One copy of 16p13.3 microdeletion including HBA1 and HBA2 was diagnosed to be a carrier of α thalassemia." (PMID 32842633, 2020). "The genes HBA1 and HBA2 of α-thalassemia are located at the end of the p arm of chromosome 16." (PMID 38075678, 2023). "Trio-WES found no mutations for thalassemia-related genes such as HBA1 and HBA2 for α-thalassemia and HBB for β-thalassemia." (PMID 36385762, 2022). "In addition to the standard GATK pipeline, specific bioinformatics tools have been used to improve the deletion detection of SMN1 and HBA1/HBA2 in spinal muscular atrophy and thalassaemia, respectively." (PMID 35314707, 2022). "In addition, we found that HBA1 and HBA2, genes involved in malaria resistance by the sickle cell and thalassemia traits, which also explains the high prevalence and specific pattern of thalassemia in the present-day DAI." (PMID 35864541, 2022). "If someone is heterozygous for --SEA/, their partner, who actually is heterozygous for large deletions including HBA1 and HBA2 in α-globin cluster, is found to be negative via conventional thalassemia gene testing." (PMID 37098594, 2023).